STMP1 (short transmembrane mitochondrial protein 1)
Description:
Microprotein involved in mitochondrial respiratory chain complex III (ubiquinol-cytochrome c oxidoreductase) and complex IV (mitochondrial cytochrome c oxidase complex) assembly. Required for the formation of mitochondrial supercomplexes (SCs). Also required for the activation of the NLRP3 inflammasome (By similarity).
Synonyms: C7orf73; PL-5283; Mm47; Mtlbn
Tractability: Antibody: UniProt predicts a signal peptide or a membrane-spanning region.
Gene: Protein-coding gene on chromosome 7 (135,662,483 to 135,693,418, forward strand). Ensembl gene ENSG00000243317.
Subcellular location: Mitochondrion inner membrane; Mitochondrion outer membrane; Mitochondrion intermembrane space
Subcellular location (Human Protein Atlas): Mitochondria
Gene Ontology:
Molecular function: protein binding
Biological process: mitochondrial respirasome assembly; mitochondrial respiratory chain complex IV assembly; mitochondrial respiratory chain complex III assembly; positive regulation of interleukin-1 beta production; positive regulation of NLRP3 inflammasome complex assembly
Cellular component: mitochondrial inner membrane; mitochondrion; mitochondrial intermembrane space; mitochondrial outer membrane; respiratory chain complex
Genetic constraint (gnomAD): Loss-of-function variants: 2 observed, 3.78 expected, observed/expected ratio (o/e) 0.53, 90% interval 0.21 to 1.55. That is too few expected variants to judge how well the gene tolerates losing a copy. Missense variants: 23 observed, 25.23 expected, observed/expected ratio (o/e) 0.91, 90% interval 0.65 to 1.29. Synonymous variants: 8 observed, 8.37 expected, observed/expected ratio (o/e) 0.96, 90% interval 0.56 to 1.66.
Homologues: Orthologues: chimpanzee STMP1 (100% identical), macaque PL-5283 (100% identical), pig STMP1 (96% identical), rabbit STMP1 (96% identical), rat Stmp1 (94% identical), mouse Stmp1 (91% identical), zebrafish stmp1 (72% identical).
Diseases named in the same sentence as STMP1 in open-access papers:
STMP1 is named in the same sentence as 4 diseases in open-access papers, as found by Europe PMC text mining. Sharing a sentence is not in itself a finding about the gene and the disease. The quoted sentences say what the papers report.
tumor (5 papers, 2023 to 2025). "Overall, STMP1 has been identified as a key regulator of tumour metastasis and a novel unit of the mitochondrial division protein machinery." (PMID 38622617, 2024). "Therefore, it is worthwhile to develop specific inhibitors of STMP1, thereby providing a potential therapeutic target for blocking tumour growth." (PMID 38622617, 2024). "In agreement, a recent study reported that Stmp1 could enhance mitochondrial fission to promote tumor metastasis." (PMID 36792584, 2023). "Furthermore, in hepatocellular carcinoma tumor metastasis, a micropeptide named STMP1 was found to interact with DRP1 in the mitochondria and promote tumor cell migration, whereas another micropeptide named JunBP was found to bind to c-Jun and promote its activation, thus driving cancer metastasis." (PMID 39311199, 2024). "The Short Transmembrane Mitochondrial Protein 1 (STMP1) is a mitochondrial peptide observed to enhance mitochondrial fission and thus promote tumor cell migration." (PMID 41347230, 2025). "Stmp1 is recently reported to interact with mitochondrial respiratory complex IV (CIV) and enhance its activity in tumor cells." (PMID 36792584, 2023). "In addition, STMP1 upregulates and activates DRP1 in cells of various types of cancer, thereby promoting mitochondrial division and enhancing tumour cell migration." (PMID 38622617, 2024).
infection (1 paper, 2022). The state of being infected such as from the introduction of a foreign agent such as serum, vaccine, antigenic substance or organism. "Here, we utilize an Stmp1 knockout (Δstmp1) to further investigate the role of Stmp1 during C. burnetii host cell infection." (PMID 35073737, 2022). "In the absence of Stmp1, cholesterol accumulates in the CCV membrane early during infection." (PMID 35073737, 2022).
STMP1 also shares sentences with these, for which no sentence is quoted: cancer (2 papers); Paget’s disease of bone (1).